GP2 (glycoprotein 2)
Description:
Functions as an intestinal M-cell transcytotic receptor specific for type-I-piliated bacteria that participates in the mucosal immune response toward these bacteria. At the apical membrane of M-cells it binds fimH, a protein of the bacteria type I pilus tip. Internalizes bound bacteria, like E.coli and S.typhimurium, from the lumen of the intestine and delivers them, through M-cells, to the underlying organized lymphoid follicles where they are captured by antigen-presenting dendritic cells to elicit a mucosal immune response.
Synonyms: ZAP75
Tractability: Small molecule: a structure with a bound ligand is known. Antibody: UniProt places it where antibodies can reach, with high confidence; its Gene Ontology location is reachable by antibodies, with high confidence; UniProt predicts a signal peptide or a membrane-spanning region.
Gene: Protein-coding gene on chromosome 16 (20,309,574 to 20,328,412, reverse strand). Ensembl gene ENSG00000169347.
Subcellular location: Zymogen granule membrane; Secreted; Cell membrane; Apical cell membrane; Membrane raft; Endosome
Pathways (Reactome):
Developmental Biology: Developmental Lineage of Pancreatic Acinar Cells
Metabolism of proteins: Post-translational modification: synthesis of GPI-anchored proteins
Gene Ontology:
Molecular function: antigen binding
Biological process: antigen transcytosis by M cells in mucosal-associated lymphoid tissue; neutrophil migration
Cellular component: apical plasma membrane; endosome; extracellular exosome; extracellular region; cell surface; external side of plasma membrane; membrane raft; plasma membrane; zymogen granule membrane
Genetic constraint (gnomAD): Loss-of-function variants: 30 observed, 37.28 expected, observed/expected ratio (o/e) 0.8, 90% interval 0.6 to 1.09. The upper end of that interval is the gene's LOEUF score, 1.09, which puts it in group 4 of 6, group 1 being the genes least tolerant of losing a copy. Missense variants: 399 observed, 440.85 expected, observed/expected ratio (o/e) 0.91, 90% interval 0.83 to 0.98. Synonymous variants: 189 observed, 172.33 expected, observed/expected ratio (o/e) 1.1, 90% interval 0.97 to 1.24.
Homologues: Orthologues: chimpanzee GP2 (99% identical), macaque GP2 (93% identical), dog GP2 (75% identical), pig GP2 (75% identical), mouse Gp2 (61% identical), rat Gp2 (61% identical), tropical clawed frog umod.3 (42% identical), tropical clawed frog umod (41% identical), zebrafish si:ch211-226h7.5 (27% identical), zebrafish si:ch211-226h7.8 (27% identical), zebrafish si:ch211-226h7.3 (27% identical), zebrafish si:ch211-226h7.6 (27% identical), and 8 more. Paralogues in human: UMOD (50% identical), OIT3 (28% identical), UMODL1 (18% identical), ZPLD1 (15% identical), TECTB (13% identical).
Diseases named in the same sentence as GP2 in open-access papers:
GP2 is named in the same sentence as 94 diseases in open-access papers, as found by Europe PMC text mining. Sharing a sentence is not in itself a finding about the gene and the disease. The quoted sentences say what the papers report.
Crohn disease (19 papers, 2012 to 2024). A gastrointestinal disorder characterized by chronic inflammation involving all layers of the intestinal wall, noncaseating granulomas affecting the intestinal wall and regional lymph nodes, and transmural fibrosis. "Elevated levels of GP2 have been found in both the exocrine pancreas and the intestinal mucosa in association with inflammatory processes in patients with Crohn’s disease or Crohn’s-like inflammation." (PMID 39427219, 2024). "The loss of tolerance to GP2 in form of GP2 autoantibodies appears to be a stratification factor of Crohns’ disease and seems related to changes of the gut microbiota composition." (PMID 39427219, 2024). "The expression of GP2 in human enterocytes suggests that the pathogenesis of Crohn’s disease is, apart from multiple other factors, associated with anti-GP2 response." (PMID 38399592, 2024). "Glycoprotein-2 (GP-2) can protect the intestinal epithelial barrier from bacteria and is associated with protection against Crohn’s disease." (PMID 33594081, 2021). "In contrast, the association of anti-GP2 with disease activity in Crohn’s disease is yet controversial." (PMID 26047356, 2015). "Autoantibodies against GP2 found in about 30% of patients with Crohn's disease appear to be associated with distinct disease phenotypes of Crohn's disease: younger age, ileocolonic location, and stricturing behavior with perianal disease." (PMID 26047356, 2015). "Glycoprotein 2 is a novel autoantigenic target in Crohn's disease located mainly in the pancreas and follicle-associated epithelium of the intestine." (PMID 23762038, 2013). "The authors also compared the levels of anti-GP2 antibodies in pouch patients to patients with UC (n = 7) and Crohn’s disease (n = 7) and reported that sera levels of anti-GP2 were similar, suggesting a similar pathophysiology in both conditions." (PMID 36778511, 2022). "Recently, IgA-class antibodies against glycoprotein 2 (anti-GP2 IgA), which were formerly linked to severe types of Crohn’s disease, were detected in sera of patients with PSC at a prevalence of 46.7–71.5%." (PMID 29636752, 2018). "Glycoprotein 2[GP2] is a specific target of pancreatic autoantibodies[PAbs] in Crohn’s disease(CD) and is involved in gut innate immunity processes." (PMID 29321484, 2018). "Pancreatic autoantibodies and recently anti-GP2 antibodies were considered specific for Crohn's disease with a sensitivity ranging from 20 to 40%." (PMID 26047356, 2015). "Remarkably, pancreatic GP2 was found to be decreased on the surface of bacteria in Crohn's disease patients compared to healthy controls." (PMID 26047356, 2015). "In conclusion, this study showed that in patients with anti-GP2 positivity, especially of IgA isotype, not only Crohn's disease but also CD should be considered as differential diagnosis." (PMID 26047356, 2015). "Autoantibodies against pancreatic secretory-granule membrane glycoprotein 2 (GP2) have been demonstrated in patients with Crohn’s disease but recently also with celiac disease (CD)." (PMID 26047356, 2015). "In contrast to Crohn's disease, where anti-GP2 antibody belongs predominantly to the IgG isotype, the predominant isotype thereof is IgA." (PMID 26047356, 2015). "Glycoprotein 2 (GP2) was discovered as the major autoantigen of Crohn’s disease (CD)-specific pancreatic autoantibodies (PAB)." (PMID 22866900, 2012). "The strikingly negative correlation between lower gastrointestinal tract localization of Crohn’s disease and presence of anti-GP2 was a characteristic feature of both studies." (PMID 22866900, 2012). "Why zymogen glycoprotein 2 (GP2), the Crohn's disease (CD)-specific pancreatic autoantigen, is the major target of humoral autoimmunity in inflammatory bowel diseases (IBD) is uknown." (PMID 23118780, 2012). "For an accurate estimation of the prevalence of anti-GP2 antibodies, a large cohort of naïve patients with Crohn's disease has to be tested." (PMID 23118780, 2012).
Crohn disease (continued). "Crohn’s disease patients with penetrating disease (B3) demonstrated a significantly lower prevalence of anti-GP2 IgG alone and of anti-GP2 IgA and/or IgG [6/42 (14.3%) vs 42/127 (33.1%) and 7/42 (16.7%) vs 44/127 (34.6%); p < 0.02, p < 0.04, respectively]." (PMID 22866900, 2012). "We assessed prevalences and levels of autoantibodies against GP2, CD-specific antibodies to endomysial antigens and tTG as well as Crohn’s disease-specific anti-Saccharomyces cerevisiae antibodies in sera of 174 patients with active CD, 84 patients under gluten-free diet (GFD) and 129 controls." (PMID 26047356, 2015). "Both CUZD1 and GP2 are expressed in pancreatic tissue in humans and pancreatic autoantibodies targeting GP2 and CUZD1 are used as Crohn’s disease-markers." (PMID 29765364, 2018). "There is evidence of a potential autoantigen function of GP2 for pancreatic autoantibody (PAB), which is involved in Crohn's disease, but the full function of the GP2 gene is yet to be elucidated." (PMID 24695378, 2014). "Finally, we characterized anti-GP2 IgA antibodies in patients with PSC and Crohn’s disease in a flow-cytometry subtyping assay." (PMID 29321484, 2018). "In two patients with coexisting inflammatory bowel disease (one with Crohn's disease and one with ulcerative colitis) anti-GP2 IgA and IgG were negative." (PMID 26047356, 2015).
breast carcinoma (17 papers, 2012 to 2025). "In a phase II clinical trial using granulocyte–macrophage colony-stimulating factor (GM-CSF) as a vaccine adjuvant, it has been reported that GP2 decreased the risk of recurrence in women with HER2/neu breast cancer." (PMID 29045460, 2017). "Examples include HER2-derived peptides (E75, AE37, and GP2) in breast cancer and gp100 or MART-1 peptides in melanoma, which have induced antigen-specific T-cell responses in early-phase investigations." (PMID 40698087, 2025). "HER2/neu peptide (GP2)-based breast cancer vaccines with GM-CSF as an adjuvant have shown promising results, with the GP2+GM-CSF vaccine combination capable of eliciting both ex vivo and in vivo immune responses." (PMID 38255214, 2024). "A phase IIb trial confirmed the outcomes of phase I regarding the safety profile of GP2 plus GM-CSF immunization in women with HER2 + operable breast cancer." (PMID 37415164, 2023). "This trial was completed in 2018, and Kaplan–Meier analysis of DFS for patients treated with GP2 immunotherapy showed 100% survival (0% breast cancer recurrence, p=0.0338) in the HER2/neu-positive adjuvant setting after a median of 5 years of follow-up." (PMID 35734599, 2022). "GP2 is another breast cancer vaccine that was evaluated for efficacy in decreasing the rate of recurrence in patients with HER2-positive breast cancer." (PMID 35216405, 2022). "A phase II clinical trial was conducted to investigate GP2 vaccine efficacy in preventing recurrence in LN+ and high-risk LN- HER2 breast cancer patients (IHC 1+–3+) in the adjuvant setting." (PMID 35734599, 2022). "GP2 vaccines have been explored as viable means to prevent breast cancer reoccurrence for HER2/neu+ patients." (PMID 33869008, 2021). "Autologous DCs from blood samples from HLA-A2 breast cancer patients were pulsed with synthesized GP2 and used to stimulate T cells in vitro." (PMID 33869008, 2021). "A polymorphism leading to a mutant GP2 protein called 2VGP2 was found at codon 655 of the HER2/neu protein and has been identified as a common mutation associated with higher risk of breast cancer." (PMID 33869008, 2021). "The results showed that the E75 and GP2 vaccines had low local and systemic toxicities and were safe for patients with breast cancer." (PMID 34526020, 2021). "The E75 and GP2 vaccines are the few therapeutic vaccines targeting HER2 currently under clinical research for patients with breast cancer." (PMID 34526020, 2021). "This phase II trial reveals that AE37 and GP2 are safe and possibly associated with improved clinical outcomes of DFS in certain subgroups of breast cancer patients." (PMID 32323103, 2020). "Here, we report the results of a multi-center, randomized, blinded, controlled phase II trial of the peptide vaccines, GP2 and AE37, as adjuvant therapy in women with high-risk breast cancer to prevent recurrence." (PMID 32323103, 2020). "With these findings, further evaluations are warranted of AE37 and GP2 vaccines given in combination and/or separately for specific subsets of breast cancer patients based on their disease biology." (PMID 32323103, 2020). "It has been shown that pretreatment of three tumor cell lines of breast cancer with trastuzumab followed by incubation with GP2 peptide induced CTL immune response." (PMID 29045460, 2017). "The immunogenic potency of the GP2 peptide for applying in HER2-positive breast cancer therapy in combination with other peptides or with the monoclonal antibody trastuzumab has been investigated." (PMID 29045460, 2017). "Our group has completed a phase I study of the concurrent administration of trastuzumab and GP2+GM-CSF in early stage HER2-positive breast cancer patients." (PMID 27589688, 2016). "It has been identified using tumor-associated lymphocytes isolated from patients with ovarian and breast cancers and a GP2 peptide vaccine is currently being evaluated in a phase II efficacy trial enrolling breast cancer patients." (PMID 23209703, 2012).
breast carcinoma (continued). "GP2 has proved to be safe and immunogenic in breast cancer patients in previous phase I studies." (PMID 36679991, 2023). "In a prospective, randomized, placebo-controlled, single blind phase IIB, multicenter clinical study, patients with operable HER2 3+ breast cancer treated with GP2 + GM-CSF after trastuzumab had a PFS rate of 100% after 5 years of follow-up compared to 89.4% in patients treated with GM-CSF alone." (PMID 37007133, 2023). "In terms of the GP2 vaccine, Clifton GT found that it could elicit an immune response in patients with breast cancer in a phase I clinical trial, thus demonstrating its immunogenicity." (PMID 34526020, 2021). "The GP2 peptide had immunogenicity in HER2/neu positive breast cancer and could be used in a multi epitope vaccine formulation." (PMID 29045460, 2017). "Our group conducted the first in-human phase I trial of GP2+GM-CSF in breast cancer patients." (PMID 27589688, 2016). "A single-blinded phase II trial (NCT00524277) has been undertaken to compare the efficacy of two HER2 vaccines, viz, GP2 and AE37 in breast cancer patients representing HER2 expression." (PMID 37415164, 2023). "In breast cancer, HER2 peptide vaccines include E75 (HER2 369-377), GP2 (HER2 654-662) and AE37 (Ii-Key/HER2 776 -790hybrid) peptides." (PMID 37007133, 2023). "These experiments confirm GP2 immunogenicity and show its potential as a peptide vaccine against HER2/neu+ breast cancer." (PMID 33869008, 2021). "The GP2 peptide is derived from the Human Epidermal growth factor Receptor 2 (HER2/nue), a marker protein for breast cancer present in saliva." (PMID 23209703, 2012). "In addition, the GP2 peptide vaccine, known as p654 with a sequenced IISAVVGIL, was confirmed to induce patients with breast cancer to generate specific CD8+ T-cells." (PMID 34526020, 2021). "It has also been shown that the GP2 based vaccines are effective in stimulating peptide-specific immunity, especially in CD8+ T cell stimulation with anti-tumor activity in human leukocyte antigen (HLA)-A2 + breast cancer patients." (PMID 29045460, 2017).
inflammatory bowel disease (10 papers, 2012 to 2025). A spectrum of small and large bowel inflammatory diseases of unknown etiology. "Exchange of serum samples among researchers and large, multi-centre, prospective studies are needed to better delineate the diagnostic and clinical relevance of anti-GP2 pancreatic antibodies and their behaviour over the course of the disease in patients with inflammatory bowel diseases." (PMID 22866900, 2012). "Consistent with the involvement of the Th17 cell/neutrophil axis, autoantibodies against neutrophil-derived antigens (ANCA) are induced and autoantibodies against gut-associated antigens (GP2) have been reported in patients with PSC-related complicated inflammatory bowel disease (IBD)." (PMID 40616144, 2025). "In inflammatory bowel disease and autoimmune liver disease, GP2 appears to be a potential autoantigenic target related to severity and tumourigenesis." (PMID 39427219, 2024). "Glycoprotein 2 (GP2) is a widely distributed protein in the digestive tract, contributing to mucosal barrier maintenance, immune homeostasis, and antigen-specific immune response, while also being linked to inflammatory bowel disease (IBD) pathogenesis." (PMID 38170255, 2024). "Furthermore, the concentration of GP2 in the stool of patients with inflammatory bowel disease, especially in that of CD patients, also showed increased concentrations of GP2 compared with that in healthy individuals." (PMID 33594081, 2021). "Since cases of septic shock are rare in patients with inflammatory bowel disease despite their disrupted intestinal epithelial barrier, pancreatic GP2 secretion in the luminal tract might explain the low incidence of sepsis in this patient population." (PMID 33594081, 2021). "Autoantibodies to four GP2 isoforms (aGP21−4) were found in patients with inflammatory bowel diseases but reactivity against specific GP2 epitopes has not been investigated in PSC yet." (PMID 30233574, 2018).